CXCL16 (C-X-C motif chemokine ligand 16)
Diseases named in the same sentence as CXCL16 in open-access papers (continued):
Sharing a sentence is not in itself a finding about the gene and the disease.
dyslipidemia (4 papers, 2020 to 2023). "In conclusion, we showed that CXCL16 expression could be an important link between metabolic syndrome, the elevated cardiovascular risk and skin involvement of psoriasis vulgaris." (PMID 35784287, 2022). "Moreover, pharmacological CXCL16 treatment abolished QGHXR-induced beneficial effects in the ethanol plus CCl4 mouse model, as evidenced by liver function biomarkers, dyslipidemia, and fibrotic indices." (PMID 36636609, 2023). "Contrary to our expectations, in the current CAD-cohort, dyslipidemia, total cholesterol (TC), and triglyceride (TG) did not have any impact on platelet-CXCL16, CXCR6 or serum sCXCL16 levels." (PMID 36232370, 2022). "In addition, patients with metabolic syndrome reveal a higher percentage of circulating CXCR6 expressing platelets and CXCR6 expressing platelet-bound neutrophils, resulting in enhanced CXCR6/CXCL16-dependent adhesion to the dysfunctional arterial endothelium." (PMID 35784287, 2022). "Platelet-CXCL16 and CXCR6 expression did not alter with dyslipidemia, triglyceride, total cholesterol, or LDL levels, but higher (>median) plasma HDL levels corresponded with decreased platelet-CXCL16 and CXCR6." (PMID 36232370, 2022). "Contrary to our expectations, platelet-CXCL16, CXCR6 or serum sCXCL16 levels were not influenced by dyslipidemia to a significant extent or even by individual lipid (total cholesterol, triglyceride) or lipoprotein (LDL) profiles, all of which are major risk factors for ACS." (PMID 36232370, 2022).
Insulin resistance (4 papers, 2020 to 2024). Increased resistance towards insulin, that is, diminished effectiveness of insulin in reducing blood glucose levels. "Another explanation is that CXCL16 by itself could be a cause of insulin resistance." (PMID 33312065, 2020). "The proinflammatory M1 macrophages are capable to secrete TNF-α and IL-6 which may lead to insulin resistance and CXCL16 upregulation." (PMID 35784287, 2022).
ischemic stroke (4 papers, 2013 to 2025). A stroke disorder caused by obstruction of blood flow to the brain, due to thrombotic (local blood clot formation) or embolic (due to a blood clot or other material traveling from another site) event. "CXCL16 level raise was associated with the development of ischemic stroke caused by atherosclerotic occlusion of carotids." (PMID 32676207, 2020). "CXCL16 is highly expressed in carotid atherosclerotic plaques, affecting plaque stability and further leading to the development of AS-related diseases such as ischaemic stroke." (PMID 40165931, 2025). "We previously demonstrated that HUMSC transplantation treated ischemic stroke in rats primarily through the cytokines secreted by the HUMSCs, such as NAP-2, angiopoietin-2, BDNF, CXCL-16, and PDGF-AA." (PMID 31588241, 2019).
meningioma (4 papers, 2016 to 2023). A generally slow growing tumor attached to the dura mater. "Due to limited material and characteristics of cultured meningioma cells (e.g. decreased proliferation and increased susceptibility to apoptosis after transfection) we chose binding experiments and kinase activation as model experiments to prove the specificity of the results by CXCL16 knockdown." (PMID 27784296, 2016). "While TGF-ß, IL-6 and OSM inhibit meningioma cell growth, SDF-1 and CXCL16 increase proliferation in cultured meningioma cells." (PMID 34503077, 2021). "Binding of Cy3-labeled s-CXCL16 to tm-CXCL16 expressed by cultured human meningioma cells was almost completely abolished after siCXCL16 knockdown in the tumor cells (upper part)." (PMID 27784296, 2016). "Since binding and signaling were abolished by siRNA silencing, we concluded that tm-CXCL16 specifically acts as a receptor for s-CXCL16 also in human meningioma cells." (PMID 27784296, 2016). "In the present investigation we now describe that cultured primary human meningioma cells exhibited high CXCL16 expression in vitro, whereas the CXCL16-specific chemokine receptor CXCR6 was mostly absent." (PMID 27784296, 2016). "In fact, Cy3-labeled s-CXCL16 was found to bind to the meningioma cells, whereas Cy3-labeled lactalbumin as a negative control did not yield any staining." (PMID 27784296, 2016). "In fact, cultured human meningioma cells considerably express CXCL16, but substantially lack CXCR6, the only known CXCL16 receptor." (PMID 27784296, 2016). "Additionally, Tregs were enriched in high-grade compared to low-grade meningiomas, whereas the expression of CXCL16, a T cell and monocyte chemoattractant, was increased in low-grade meningiomas." (PMID 36768342, 2023). "Therefore, we analyzed binding, intracellular signaling effects and different biological readouts in cultured primary human meningioma cells upon stimulation with s-CXCL16." (PMID 27784296, 2016). "Additionally, CXCL16 was able to reduce caspase-3 activity after camptothecin treatment in CXCR6-negative but tm-CXCL16-positive cultured primary human meningioma cells." (PMID 27784296, 2016). "In contrast, control siRNA transfected meningioma cells were still able to bind s-CXCL16." (PMID 27784296, 2016). "On protein level, we could detect CXCL16 expression by immunocytochemistry and western blots of meningioma cell membrane preparations yielding specific bands for the transmembrane (tm-)CXCL16." (PMID 27784296, 2016). "Targeting the tumor promoting effects of CXCL16 might be a promising therapy amendment e.g. for atypic meningiomas and other tumors with limited treatment options." (PMID 27784296, 2016). "In fact, we could show that both effects – activation of proliferation and rescue of apoptosis – were triggered by s-CXCL16 in cultured CXCR6-negative, but tm-CXCL16-positive meningioma cells." (PMID 27784296, 2016). "Apart from that, we could show that solid human meningiomas - the second most common intracranial tumors - are also characterized by high expression levels of CXCL16 while CXCR6 expression is more restricted." (PMID 27784296, 2016). "However, although cultured human meningioma cells lack the CXCL16-specific receptor CXCR6, stimulation with s-CXCL16 was able to transduce intracellular signaling effects." (PMID 27784296, 2016). "In a next step, we aimed to show that tm-CXCL16 expression is mandatory to the signaling mediated by s-CXCL16, to further support the hypothesis of “inverse signaling” in human meningioma cells." (PMID 27784296, 2016). "Thus, regarding the fact that the positive control yielded proliferation of meningioma cells within the same range (P1 = 130 %; P3 = 132 %; P4 = 126 %; control = 100 %), CXCL16 stimulation clearly yielded proliferative effects in these cells." (PMID 27784296, 2016). "Now, we hypothesized that “inverse signaling” via tm-CXCL16 might also take place in meningiomas, a completely different, benign tumor entity." (PMID 27784296, 2016).
meningioma (continued). "Thus, “inverse signaling” of the transmembrane chemokine CXCL16 occurs in cultured primary human meningioma cells, and is involved in progression of human meningiomas." (PMID 27784296, 2016). "Thus, the inverse signaling mechanism of CXCL16 we here describe for meningiomas may occur in a variety of benign and malignant tumors, modulating amongst others the interplay between tumor and immune cells and influencing on tumor progression." (PMID 27784296, 2016). "Therefore, we wanted to know whether stimulation with s-CXCL16 could induce these biological responses in cultured primary human meningioma cells." (PMID 27784296, 2016). "We used quantitative reverse-transcription polymerase chain reaction, immunocytochemistry and western blot to detect CXCL16 and CXCR6 in human meningioma cells isolated from 28 human meningiomas." (PMID 27784296, 2016). "Summarized, in cultured primary human meningioma cells the classical CXCL16 receptor CXCR6 is lost, but nevertheless CXCL16 is still able to bind to and transduce signals into the cells resulting in increased proliferation and rescue of apoptosis of the cells." (PMID 27784296, 2016). "Subsequently, we stimulated cultured human tm-CXCL16-positive, CXCR6-negative meningioma cells with recombinant s-CXCL16 and analyzed binding, signaling and biological effects using RNAi silencing to verify specificity." (PMID 27784296, 2016). "We initially measured CXCL16 and CXCR6 mRNA expression in cultured meningioma cells used in our experimental settings." (PMID 27784296, 2016). "We measured in a next step if cultured CXCR6-negative human primary meningioma cells were able to bind s-CXCL16 and transduce signaling effects." (PMID 27784296, 2016). "Thus, we concluded that human meningioma cells cultivated from different patients samples substantially express CXCL16 expression while CXCR6 is absent." (PMID 27784296, 2016). "To understand which biological consequences were induced after s-CXCL16 induced “inverse signaling”, we investigated proliferation effects and whether s-CXCL16 could prevent apoptosis in CXCR6-negative but tm-CXCL16-positive cultured primary human meningioma cells." (PMID 27784296, 2016).
nephritis (4 papers, 2012 to 2023). Inflammation of renal tissue. "The ligand for CXCR6, CXCL16, was recently reported to be elevated in juvenile SLE patients, and was strongly associated with alopecia, malar rash, and nephritis." (PMID 35833127, 2022). "They found that serum CXCL16 level was markedly higher in juvenile patients with SLE than healthy controls, as well as associated with SLE-related disease indexes such as disease activity and severity of relevant nephritis, ultimately speculated CXCL16 may exert biological functions in LN." (PMID 37393391, 2023). "Likewise, among active nephritis patients, VCAM-1 and CXCL16 levels as well as the urine protein:creatinine ratio were not different between the patients who received a specific medication and those who did not." (PMID 22788914, 2012). "Among the nonactive nephritis patients, therefore, VCAM-1, CXCL16 and MCP-1 levels and the urine protein:creatinine ratio were not different between the patients who received a specific medication and those who did not." (PMID 22788914, 2012).
renal carcinoma (4 papers, 2015 to 2017). A carcinoma arising from the epithelium of the renal parenchyma or the renal pelvis. "Interestingly, transmembrane CXCL16 in renal cancer cells was found to act proadhesive but antimigratory." (PMID 28260841, 2017). "On the other hand, high expression of CXCL16 but low ADAM10 expression, which presumably leads to less CXCL16 shedding and accumulation of transmembrane CXCL16, correlated with longer survival in renal cancer patients." (PMID 28260841, 2017). "Although no specific data are available on CXCL16 and bladder cancer, our results are in line with those reported in renal cancer, where CXCL16 correlated inversely with tumour stage, i.e. high tissue levels of CXCL16 was associated with lower stage and better patient survival." (PMID 29285224, 2017).
Stroke (4 papers, 2020 to 2022). Sudden impairment of blood flow to a part of the brain due to occlusion or rupture of an artery to the brain. "Given that the listed risk factors were closely related to stroke, the authors supposed that the role of a high CXCL16 in stroke was mainly mediated through an inflammatory response and contributed to the plaque formation and rupture." (PMID 32676207, 2020). "Several studies have shown that immune responses including IL6, IgA, CXCL16, TNFSF4, and IL10 were involved in stroke." (PMID 31899762, 2020).
triple-negative breast carcinoma (4 papers, 2016 to 2023). An invasive breast carcinoma which is negative for expression of estrogen receptor (ER), progesterone receptor (PR), and human epidermal growth factor receptor 2 (HER2). "Here, the authors show that in patients with triple negative breast cancer resident monocytes activate cancer-associated fibroblasts and induce production of CXCL16, which acts as a monocyte chemoattractant, resulting in an amplificatory feedback loop." (PMID 27725631, 2016). "This is important in triple-negative breast cancers, although not all cell lines of this type of cancer increase the expression of CXCL16 in fibroblasts." (PMID 33800554, 2021).
Cerebral ischemia (3 papers, 2016 to 2021). Restriction of arterial blood supply to the brain associated with insufficient oxygenation to support the metabolic requirements of the tissue. "Recently we reported that CXCL16, acting on astrocytes, drives neuroprotective effects in brain ischemia, counteracting glutamate excitotoxic damage." (PMID 30542347, 2018).
fatty liver disease (3 papers, 2014 to 2024). A reversible condition wherein large vacuoles of triglyceride fat accumulate in liver cells via the process of steatosis. "Taken together, our study provides experimental evidence that targeting the chemokine CXCL16 is a promising strategy in fatty liver diseases." (PMID 25372401, 2014). "In addition, hepatic TG and FFA levels were markedly depleted after QGHXR treatment alone but increased by CXCL16 and QGHXR cotreatment, suggesting that CXCL16 treatment suppressed QGHXR-induced effects on hepatic steatosis." (PMID 36636609, 2023).
glomerulonephritis (3 papers, 2020 to 2021). A renal disorder characterized by damage in the glomeruli. "More relative to AKI, a study involving the pharmacological inhibition of CXCL16 using an antiserum generated against CXCL16 showed reduced progression of anti-GBM glomerulonephritis suggested to be through its role in leukocyte influx." (PMID 33805488, 2021). "Inhibition of CXCL16 has been linked to ameliorating effects in a variety of inflammatory related diseases such as liver inflammation and steatohepatitis, anti-GBM glomerulonephritis and the regulation of CIAKI." (PMID 33805488, 2021). "As reported CXCL16 and its CXCR6 receptor play important role in the recruitment of natural killer T cells and in the protection of animals in glomerulonephritis models." (PMID 32218590, 2020).
hepatic disease (3 papers, 2010 to 2023). "CXCL16 exists on the surface of antigen-presenting cells and hepatocytes in patients with hepatic disorders." (PMID 36636609, 2023). "Previous studies suggested that CXCL16 plays a vital role in liver disorders." (PMID 36636609, 2023). "Similar induction of CCL21, CXCL16, CXCL9 and CXCL13 in the liver in other models of hepatic disease suggests that common mechanisms regulate the recruitment of lymphocytes to the liver following inflammation." (PMID 20502518, 2010).
HIV-1 infection (3 papers, 2019 to 2025). The type species of lentivirus and the etiologic agent of acquired immunodeficiency syndrome (AIDS). "Upregulated C1QA, CD163, and CXCL16 and downregulated LMNA and CLU were identified as age-associated genes tied to HIV-1 infection." (PMID 38399364, 2024). "Upon HIV-1 infection of MDMs, we also observed a higher level of ISG induction in MDMs from older donors, including IRF5, as well as several known IRF5-responsive genes, such as CXCL16, CCL5, and CD80." (PMID 40493408, 2025). "These upregulated genes were primarily ISGs, including IRF5 and IRF7, as well as several known IRF5 target genes, including CCL5, CXCL16, and IL23A, suggesting that MDMs from older individuals display an enhanced IRF5-dependent innate immune response to HIV-1 infection." (PMID 40493408, 2025).
Hypertension (3 papers, 2016 to 2022). The presence of chronic increased pressure in the systemic arterial system. "Platelet-CXCL16 levels were median CXCL16-MFI (25th; 75th percentile) = 42.65 (37.89; 52.48) for w/o hypertension vs. 50.20 (38.70; 59.90) for w/hypertension." (PMID 36232370, 2022). "Hypertension seemingly did not affect platelet-CXCL16, serum sCXCL16 or CXCR6 surface expression on platelets." (PMID 36232370, 2022). "The presence or absence of hypertension did not influence platelet-CXCL16, platelet CXCR6 or serum levels of sCXCL16 (Figure 4Di–Diii)." (PMID 36232370, 2022).
inflammatory bowel disease (3 papers, 2011 to 2021). A spectrum of small and large bowel inflammatory diseases of unknown etiology. "CXCL16 is elevated in patients with inflammatory bowel disease, and Cxcl16−/− mice display less inflammation in a murine model of enterocolitis." (PMID 22241984, 2011). "CXCL16 can also be taken as a marker of inflammatory bowel disease (IBD)." (PMID 33800554, 2021).
influenza (3 papers, 2015 to 2023). An acute viral infection of the respiratory tract, occurring in isolated cases, in epidemics, or in pandemics; it is caused by serologically different strains of viruses (influenzaviruses) designated A, B, and C, has a 3-day incubation period, and usually lasts for 3 to 10 days. "A recent study showed that lung epithelial cells express the ligand for CXCR6 (CXCL16), and that CXCR6-CXCL16 interaction drives CD8 T cell localization within the lungs after an influenza infection." (PMID 37662932, 2023). "NKT cell accumulation within these tissues and influenza-specific mucosal IgA levels were reduced in CXCL16−/− mice." (PMID 26074921, 2015). "It would be interesting to determine whether influenza vaccination in conjunction with intranasal α-GalCer administration also increases the NKT cell population in the lung and/or airways, and if so, whether this increase is also impaired in CXCL16−/− mice." (PMID 26074921, 2015).
ischemia (3 papers, 2014 to 2022). A hypoperfusion of the BLOOD through an organ or tissue caused by a PATHOLOGIC CONSTRICTION or obstruction of its BLOOD VESSELS, or an absence of BLOOD CIRCULATION. "In vivo experiments using CXCR6 knock-out mice have demonstrated that the disruption of the CXCL16/CXCR6 signaling had a cardioprotective effect against ischemia-reperfusion injury." (PMID 35625854, 2022). "Since CXCL16 signaling is determinant in reducing brain damage, we measured CXCL16 expression in the brain upon ischemia." (PMID 25071451, 2014). "Since we have shown that CXCL16 is neuroprotective in ischemia, and neuroinflammation plays a role in brain damage following ischemic insult, we considered the possibility that CXCL16, acting on CXCR6 expressed by microglia cells, might provide protective effects also modulating microglia phenotype." (PMID 30542347, 2018).
metastatic tumors (3 papers, 2014 to 2019). "Amongst these, CXCL16 showed the highest fold change in CAFs from metastatic tumors compared to normal breast or primary tumors (5.34 and 6.436, respectively)." (PMID 28649646, 2017). "In addition, CXCL16 expression induced the infiltration of M1 macrophages into metastatic tumors and inhibited liver metastasis by releasing TNF-α, thereby inducing the apoptosis of CXCL16-expressing metastatic CRC cells." (PMID 25495942, 2014). "The two-color immunofluorescence staining with anti-CXCL16 and anti-EpCAM mAb and consecutive-sections-staining procedure with anti-CEA and anti-CXCL16 in the primary tumor tissues and lymph node metastasis suggest that CXCL16 is produced mainly by primary tumor cells and metastatic tumor cells." (PMID 31752131, 2019).